TF (transferrin)
Diseases named in the same sentence as TF in open-access papers (continued):
Sharing a sentence is not in itself a finding about the gene and the disease.
Sepsis (continued). "All together, the inclusion of TF-Sat in the widely used sepsis prognostic scores like SOFA and, to a lesser extent, SAPS II may improve their accuracy and enhance predictions especially for patients demonstrating high score values but low TF-Sat." (PMID 33014378, 2020). "TF expression provokes widespread thrombosis in the microcirculation of various organs, contributing to multiple organ dysfunction, a major determinant of mortality in sepsis 104-106." (PMID 32792851, 2020). "Preventing tissue-factor-(TF-) mediated systemic coagulopathy improves outcome in models of sepsis." (PMID 22195278, 2012). "Sepsis (odd ratio 5.24), among the clinical variables and IL-10 (odd ratio 1.24, 95% confidence interval (CI): 0.00–2.19) and transferrin (odd ratio 0.45, CI: 0.00–6.43) among the stress and nutritional mediators were independently associated with the development of MOSF (P < .0001)." (PMID 20490277, 2010). "When a multiple linear regression analysis (stepwise method) was used, classified sepsis (r2 = 0.25, P = .003), transferrin (r2 = 0.21, P = .01), IL-6 (r2 = 0.31, P = .002), and the NI (r2 = 0.52, P = .001) were independently associated with the PRISM score (F = 12, P = .0000)." (PMID 20490277, 2010). "Genes such as MYC (a transcription factor, TF), SELL, and LGALS3 (associated with cold shock domain-containing protein A) may act as upstream regulators or potential therapeutic targets in the context of glycosylation dysfunction related to sepsis." (PMID 40672940, 2025). "In addition, the expression of tissue factor (TF) in activated ECs initiates intravascular coagulation and promotes platelet aggregation and microthrombi formation, aggravating microcirculatory disturbance and tissue injury in sepsis." (PMID 39822760, 2025). "Furthermore, we identified transferrin saturation as a stand-alone predictor of sepsis survival and as a parameter of iron metabolism which may in a combined model improve the prediction power of the SOFA score." (PMID 33014378, 2020). "Genome-wide association studies (GWAS) data for SI, serum ferritin (SF), serum transferrin (STF), transferrin receptor (TFRC), sepsis, and cardiomyopathy were obtained from the EBI website." (PMID 41323136, 2025). "In sepsis, inflammatory mediators such as TNF-α and IL-6 enhance TF expression on endothelial cells, promoting thrombosis." (PMID 40226813, 2025). "BMP6 did not correlate with ferritin (r = −0.024, p = 0.823), iron (r =−0.084, p = 0.467), or transferrin (r = −0.006, p = 0.958) in SIRS/sepsis/septic shock patients when patients with liver cirrhosis were excluded." (PMID 39200147, 2024). "Ferritin (p = 0.561), iron (p = 0.273), and transferrin (p = 0.146) were similar in patients with SIRS, sepsis, and septic shock." (PMID 39200147, 2024). "Iron and transferrin levels of the patients were lower, and ferritin levels were higher in SIRS/sepsis/septic shock patients when compared to the normal ranges of these measures." (PMID 39200147, 2024). "Recent findings demonstrated that parameters of iron metabolism, particularly transferrin and TSAT, can be utilized as strong outcome predictors for diverse groups of patients with sepsis." (PMID 39000113, 2024). "On the contrary, serum iron and transferrin levels were decreased in ICU subjects, with the lowest values among sepsis patients." (PMID 37046922, 2023). "Therefore, an elevated TF-Sat may indicate a dysfunction of the macrophage system during sepsis." (PMID 33014378, 2020). "In disseminated intravascular coagulation due to sepsis further TF expression on monocytes and macrophages occurs and needs to be considered in patients receiving ECMO as sepsis is a common accompanying problem." (PMID 30619862, 2018). "In addition, there was no significant change detected during the experimental period (72 h) in serum iron, TIBC, and serum transferrin between the sham and CLP-induced sepsis groups." (PMID 39949667, 2025).
Sepsis (continued). "Ferritin, iron, and transferrin levels were not related to bacterial infection in patients with SIRS/sepsis/septic shock (p > 0.05 for all)." (PMID 39200147, 2024). "Even in most recent guidelines for COVID (COVID-19) or in reports about sepsis, there is no mention of ferritin, transferrin, or other iron parameters." (PMID 33685484, 2021). "This is illustrated by the requirement for human and not bovine transferrin or lactoferrin as an exogenous iron source for establishing a mouse model for sepsis and invasion infection by the human pathogen Neisseria meningitidis." (PMID 32158772, 2020). "Interestingly, iron and TSAT levels were significantly decreased in sepsis survivors, and transferrin levels were lower in non-survivors." (PMID 39000113, 2024). "In our cohort, individuals having received RBC transfusions within the last 3 months before ICU admission displayed higher serum iron, ferritin and TF-Sat values and significantly lower hematocrit levels as compared to non-transfused sepsis patients at initial presentation to the ICU." (PMID 33014378, 2020).
Alzheimer disease (44 papers, 2009 to 2026). A progressive, neurodegenerative disease characterized by loss of function and death of nerve cells in several areas of the brain leading to loss of cognitive function such as memory and language. "Since then, brain-type transferrin was proposed to be diagnostic for many neurological diseases such as Alzheimer’s disease, vanishing white matter disease, or spontaneous intracranial hypotension." (PMID 36768261, 2023). "Ca2+/calmodulin-dependent protein kinase kinase 2 controls important neuronal processes and its loss leads to aberrant transferrin phosphorylation and trafficking which makes it a potential biomarker for Alzheimer’s disease." (PMID 31144035, 2019). "Mutations in transferrin lead to an increased risk of Alzheimer’s disease." (PMID 30220890, 2018). "The ratio of brain-type transferrin to serum-type transferrin in the CSF is altered in neurological diseases such as Alzheimer’s disease and Parkinson’s disease, demonstrating the clinical potential of brain-derived glycoproteins in the CSF." (PMID 36768261, 2023). "For example, an increase of transferrin mRNA levels was observed in the temporal and frontal cortices of patients with Alzheimer’s disease." (PMID 35053014, 2021). "The results illustrate that (Schedule 3), a total of 128 transcription factors have distinguished transcriptional regulation for dysfunction modules of neuronal apoptosis in Alzheimer's disease, referring to 157 TF-Module regulatory pairs." (PMID 34992508, 2021). "A recent study evaluated the improvement of bioavailability and brain targeting for Alzheimer’s disease (AD) using transferrin-conjugated PEGylated liposome." (PMID 34713363, 2021). "Aim of this study is to explore glycan-biomarkers on transferrin (Tf) for Alzheimer’s disease (AD) in cerebrospinal fluid (CSF)." (PMID 34564432, 2021). "Metals that have a similar binding affinity to human serum transferrin as that of iron prove to be potential indicators of Alzheimer's disease." (PMID 35515673, 2020). "A close association between EEG/MEG abnormalities and some markers of the oxidative stress or free radical scavengers (iron, peroxides and transferrin) have been found in patients with Alzheimer disease and stroke." (PMID 24245542, 2013). "YY1 expression can control iron-transferrin homeostasis in an age-dependent manner, regulate cell senescence and Alzheimer's disease-related amyloid processing." (PMID 21179406, 2010). "Human transferrin (htf) plays a crucial role in regulating the balance of iron within brain cells; any disruption directly contributes to the development of Neurodegenerative Diseases (NDs) and other related pathologies, especially Alzheimer’s Disease (AD)." (PMID 38495092, 2024). "Due to the minimal difference in binding energies of the gallium–human serum transferrin complex and the indium–human serum transferrin complex to the iron–human serum transferrin complex, we determined that gallium and indium could be potential indicators of Alzheimer's disease." (PMID 35515673, 2020). "However, the interacting SNPs can also be located within different genes as in the case of Pro589Ser (rs1049296) in the transferrin (TF) gene and Cys282Tyr (rs1800562) in the haemochromatosis (HFE) gene which interact so as to increase the risk of Alzheimer disease." (PMID 23820649, 2013). "Moreover, an up-regulation of HMOX1 expression (resulting in increase of oxidative stress and sequestration of iron non-linked to transferrin in the mitochondrial department) has been found in the brains of patients with PD, Alzheimer's disease, and multiple sclerosis." (PMID 26313808, 2015). "Additionally, TF and TFRC levels show positive correlations with iron content in AD brains, suggesting their potential role in iron dysregulation in Alzheimer’s disease." (PMID 39669708, 2024). "Without this defective transferrin, the neurotoxic effects of aluminum in Alzheimer disease and Down syndrome can be avoided." (PMID 34541400, 2022).
hereditary hemochromatosis (43 papers, 2012 to 2025). An inherited metabolic disorder characterized by iron accumulation in the tissues. "At present, accumulating studies have documented the association between transferrin saturation and hereditary hemochromatosis (HH), but relatively little is known about the role of transferrin saturation in OA." (PMID 36145059, 2022). "In women, increased genetically instrumented transferrin saturation was associated with incident haemochromatosis (β=0.25, P<0.001) and osteoarthritis (β=0.015, P=0.002)." (PMID 30651232, 2019). "Literally, high levels of serum iron and transferrin saturation are commonly reported in the setting of acute liver failure or chronic liver disease, but the presence of hereditary hemochromatosis-related mutations as indicators of primary hemochromatosis is exceedingly rare." (PMID 39050104, 2024). "Haemochromatosis is characterized by transferrin saturation greater than 55% and serum ferritin concentrations exceeding 200 μg/L in women and 300 μg/L in men." (PMID 39687529, 2024). "A transferrin saturation exceeding 45% (the cut-off used for suspicion of haemochromatosis) was detected in six (4%) WT patients compared to 13 (14%) patients carrying a mutation (p = 0.01)." (PMID 38392579, 2024). "Considering the possibility of haemochromatosis, ferritin and transferrin saturation tests were performed, revealing markedly elevated ferritin levels (3945 ng/mL) and transferrin saturation (110%)." (PMID 39687529, 2024). "Iron studies, including ferritin and transferrin saturation, are performed to evaluate hereditary hemochromatosis (HH)." (PMID 37711943, 2023). "Both had high serum iron transferrin saturation and ferritin levels, and clinical presentations consistent with hereditary hemochromatosis." (PMID 38057357, 2023). "Mutations in HFE lead to hereditary hemochromatosis (MIM 235200), while mutations in TF lead to hereditary atransferrinemia (MIM 209300)." (PMID 35606419, 2022). "In the setting of normal transferrin saturation, hereditary hemochromatosis (HH) is unlikely but further evaluation for HH with HFE gene analysis is indicated if the transferrin saturation is ≥ 45%." (PMID 36090909, 2021). "Physiologically, TfR mediates iron uptake into cells by binding and importing iron-loaded transferrin, which also binds to the hereditary hemochromatosis protein in the intestine to regulate iron uptake by blocking transferrin binding." (PMID 33083102, 2020). "As an example, in hereditary hemochromatosis, iron is transported from the intestine to the liver via the portal vein (as transferrin) to be deposited in periportal hepatocytes." (PMID 33046755, 2020). "Elevated ferritin, iron, and transferrin saturation suggested probable hepatitis due to haemochromatosis." (PMID 26977326, 2016). "This is due to the model having fixed extracellular transferrin-bound iron concentration, in contrast to haemochromatosis where this concentration increases due to higher absorption in the intestine." (PMID 24244122, 2013). "Although Tf-dependent iron uptake is probably predominant under normal circumstances, in the case of iron overload (e.g., hereditary hemochromatosis and β-thalassemia), the iron binding capacity of transferrin can be exceeded." (PMID 23807651, 2013). "Increased concentrations of iron and ferritin in the blood, together with high transferrin saturation, may indicate a potential diagnosis of haemochromatosis." (PMID 39200108, 2024). "Investigating the relatives of patients with familial diseases, including haemochromatosis or Wilson’s disease, would be an indication for the specific relevant tests: ferritin and transferrin saturation, haemochromatosis genotype, caeruloplasmin and urinary copper." (PMID 29122851, 2018).
hereditary hemochromatosis (continued). "This leads to hereditary hemochromatosis (HH), a genetically heterogenous autosomal recessive disorder of iron metabolism characterized by gradual buildup of unshielded non-transferrin bound iron (NTBI) in plasma and excessive iron deposition in tissue parenchymal cells." (PMID 30420953, 2018). "Hereditary hemochromatosis may be suspected, as in this case, with the presentation of unexplained fatigue, with a probable first- or second-degree relative diagnosed with the same, with high serum ferritin and transferrin saturation (>45%)." (PMID 40568254, 2025). "Similar to WD, haemochromatosis featured by the accumulation of iron in the liver, is associated with elevated serum ferritin and increased serum transferrin saturation rather than serum iron level and it is mostly reported to have an association with hepatocellular carcinoma." (PMID 36923697, 2023). "Genetic variants leading to excess body iron occur mainly in the haemochromatosis (HFE) gene but are also seen in hepcidin (hepcidin antimicrobial peptide (Hamp)), transferrin receptor 2 (TFR2), solute carrier family 40 member 1 (SLC40A1), haemojuvelin (HJV) and transferrin (TF) genes." (PMID 32609760, 2020). "If the serum ferritin level and transferrin saturation are both elevated, further assessment should be undertaken for the presence of HFE‐related haemochromatosis, due to p.Cys282Tyr homozygosity, in individuals with European ancestry or if there is uncertainty regarding European ancestry." (PMID 40013463, 2025). "Almost half of the patients were tested for chronic viral hepatitis B and C before referral (n = 150, 46.4%), and 120 patients (37.2%) tested negative for haemochromatosis (normal transferrin saturation and serum ferritin levels)." (PMID 33494361, 2021). "NTBI can be detected in patients with non-transfusion-dependent hereditary anemia and hereditary hemochromatosis with moderately increased transferrin saturation (TSAT) levels." (PMID 32041196, 2020). "The pathogenesis of hereditary hemochromatosis involves uncontrolled iron absorption and efflux into the bloodstream (at a rate up to 8–10 mg/day), gradually leading to oversaturation of transferrin and buildup of non-transferrin-bound iron (NTBI)." (PMID 30420953, 2018). "Laboratory tests showed elevated ferritin and transferrin saturation suggesting probable hepatitis due to haemochromatosis, which was ruled out through a negative of C282Y and H63D genotypes and the liver biopsy." (PMID 26977326, 2016).
lung carcinoma (40 papers, 2005 to 2025). "For instance, higher ferritin levels but lower transferrin levels were associated with an increased risk of lung cancer." (PMID 39246326, 2024). "In the present study, we conducted a 2-sample MR analysis using publicly available data to explore the causal relationship between 4 different iron biomarkers and lung cancer risk, including serum iron, ferritin, transferrin saturation, and transferrin." (PMID 35866826, 2022). "To better understand the molecular mechanism of AT2 and basal underlying the pathogenesis of lung cancer, we constructed a TF regulatory network based on upregulated genes." (PMID 35027529, 2022). "On the other hand, a more recent study on the correlation of serum iron with the risk of lung cancer, revealed a causal correlation between serum iron, ferritin, transferrin, transferrin saturation and lower risk of lung squamous cell carcinoma, potentially suggesting a protective effect of iron." (PMID 39246326, 2024). "Survival analysis performed in this study revealed that higher body iron content (mainly expressed by higher iron level and transferrin saturation) detected prior to treatment may be associated with decreased risk of death among lung cancer patients." (PMID 30640897, 2019). "Expanding on this concept, transferrin-conjugated, doxorubicin-loaded, lipid-coated poly d,l-lactic-co-glycolic acid nanoparticles (TF-LPs) were developed as targeted vectors for lung cancer therapy." (PMID 38794306, 2024). "Unfortunately, this has hardly improved since 2014: in our study transferrin saturation was determined in only 19.5% of patients overall and in 16.9% and 15.4% of patients with lung cancer and malignant lymphoma, respectively." (PMID 38240843, 2024). "Further studies on larger populations are necessary to determine a possible interaction of these SNPs, especially in HFE, TFR1, TF, with iron metabolism in lung cancer." (PMID 30640897, 2019). "A few studies have examined the association of serum Fe concentration and/or Fe metabolism parameters (transferrin, ferritin, TIBC) with lung cancer risk but the results are also inconclusive." (PMID 30640897, 2019). "A significantly higher transferrin saturation was observed in 50 men with lung cancer compared to 3113 cancer-free controls (33.9% vs. 30.07%, p<0.05) from the NHANES I cohort of over 14,000 individuals from USA." (PMID 30640897, 2019). "We also found that higher transferrin saturation (p = 0.01) and lower TIBC (p<0.01) are associated with better survival of lung cancer patients." (PMID 30640897, 2019). "To actively target lung cancer cells, we have developed a conjugate of the apoptosis inducing protein cytochrome c with transferrin because the transferrin receptor is overexpressed by many rapidly dividing cancer cells." (PMID 29649293, 2018). "Confocal results demonstrated the cellular uptake of the cytochrome c-transferrin conjugate by transferrin receptor overexpressing A549 lung cancer cells." (PMID 29649293, 2018). "Using the 5D-SPT technique, the rotational motions of transferrin-coated gold nanorods on the cell membrane and during the subsequent endocytosis by A549 human lung cancer cells were continuously followed." (PMID 29026088, 2017). "Various receptors, including folate receptor alpha (FRA), epidermal growth factor receptor (EGFR), integrins, CD44, and transferrin, are known to be overexpressed in lung cancer cells." (PMID 28290155, 2017). "In one study, serum transferrin level was found to be lower in the lung cancer group than in the control group and therefore it was noted as suitable for monitoring prognosis." (PMID 24592197, 2014). "In the tumor, it has recently emerged as important players in growth and metastasis, but previous studies have lacked information about the downstream signal pathways induced by the inhibition of the TF expression via TF-siRNA in lung cancer cells." (PMID 21619686, 2011).